SOD3 (superoxide dismutase 3)
Diseases named in the same sentence as SOD3 in open-access papers (continued):
Sharing a sentence is not in itself a finding about the gene and the disease.
coronary artery disease (14 papers, 2012 to 2025). "Juul et al12 reported that the SOD3 p.R231G variant was a risk factor for ischemic heart disease in 9,188 participants from the Copenhagen City Heart Study." (PMID 33879836, 2021). "Individuals who carry SOD3R213G exhibit increased plasma concentrations of SOD3, and have increased risk of ischemic heart disease." (PMID 32004354, 2020). "The myocardial overexpression of SOD3 inhibits left ventricular remodeling after myocardial infarction, and the SOD3 overexpression has potential clinical utilization in coronary heart disease." (PMID 33936387, 2021). "SOD3 was a key extracellular antioxidative stress enzyme and played a pivotal role against cardiac oxidative stress, and the SOD3 expression was reduced in patients with coronary heart disease." (PMID 31780868, 2019). "The vascular SOD3 activity was severely reduced in coronary artery segments with stenoses of patients with coronary artery disease and SOD expression and activity being reduced in coronary atherosclerotic plaque." (PMID 28044093, 2016). "The vascular SOD3 activity was severely reduced in coronary artery segments with stenoses of patients with coronary artery disease and SOD3 expression and activity were reduced in coronary atherosclerotic plaque." (PMID 28044093, 2016). "SOD3 polymorphisms are associated with COPD, coronary artery disease, myocardial infarction as well as acute lung injury and related mortality." (PMID 22529530, 2012). "The SOD3 variant, SOD3R213G, results from substitution of arginine to glycine at amino acid 213 (R213G) in its heparin binding domain (HBD) and is a common genetic variant, reported to be associated with ischemic heart disease." (PMID 32004354, 2020). "SOD3 variant R213G (SOD3R213G), the substitution of arginine to glycine at amino acid 213 in the HBD, is a common human gene variant and is known to be associated with many diseases, including ischemic heart disease and vascular impairment." (PMID 32004354, 2020). "Patients with coronary artery disease demonstrated elevated expression of SOD1 and SOD2 but not SOD3." (PMID 38389898, 2024).
COVID-19 (14 papers, 2020 to 2025). A disease caused by infection with severe acute respiratory syndrome coronavirus 2. "Conversely,proteins related to antioxidant defense mechanismswere significantly downregulated in the COVID-19 group, particularlyextracellular superoxide dismutase (SOD3)." (PMID 40584364, 2025). "SOD3, an antioxidant enzyme, has been reported to be downregulated in the urine of severe COVID-19 cases." (PMID 36930526, 2023). "Older COVID-19 patients also had lower levels of the antioxidant enzyme superoxide dismutase 3 SOD3, and this finding was related to disease severity." (PMID 36851096, 2023). "There is evidence of a link between decreased expression of the antioxidant enzyme superoxide dismutase 3 (SOD3) in the lungs of elderly patients with COVID-19 and disease severity." (PMID 35216286, 2022). "This leads us to think about the role of using GSTp1 (glutathione S-transferase-pi), a cytosolic detoxification enzyme, and SOD3 (extracellular superoxide dismutase-ECSOD) in COVID-19 disease management." (PMID 35314591, 2022). "Currently, there’s no published evidence linking SOD3 gene polymorphisms (such as rs1799895, rs2536512, or others) to COVID-19 susceptibility or severity." (PMID 41209585, 2025). "In support of the involvement of RONS in COVID-19 pathogenesis, the levels of superoxide dismutase 3 (SOD3) in the lungs of elderly patients and children may be a factor for the different disease progression in these age groups." (PMID 37175181, 2023). "Moreover, there is decreased expression of the antioxidant enzyme SOD3 in the lungs of elderly COVID-19 patients." (PMID 37762492, 2023). "Older COVID-19 patients, who have a higher risk of mortality from the disease, were shown to express much less SOD3 from their AEC II than younger patients, suggesting an important role of SOD3 in protecting against the cytokine storm." (PMID 33014275, 2020). "While SOD3 variants have been implicated in lung function and susceptibility to chronic respiratory conditions (e.g., COPD), and SOD3 is anatomically and functionally relevant to lungs, no studies to date have reported associations between SOD3 SNPs and COVID-19 outcomes." (PMID 41209585, 2025). "Following previous studies, evidencing that SOD administration can decrease the severity of respiratory illness, the authors propose to better evaluate if lung-specific delivery of SOD3 related antioxidants, in combination to other anti-virals, may improve COVID-19 outcomes in the elderly." (PMID 33101211, 2020). "More importantly, the downregulation of redox-active genes, such as superoxide dismutase 3 (SOD3), activating transcription factor 4 (ATF4), and metallothionein 2A (M2TA), observed in the lungs of elderly COVID-19 patients seemed to be connected to the severity of the disease." (PMID 34202515, 2021).
atherosclerosis (13 papers, 2010 to 2025). A disease characterized by the build-up of fatty material and calcium deposition in the arterial wall resulting in partial or complete occlusion of the arterial lumen. "Oxidative stress was related to atherosclerosis, and superoxide dismutase 3 (SOD3) was the major antioxidant molecule." (PMID 31780868, 2019). "Atherosclerosis was associated with decreased NO bioactivity after MDA-mediated inhibition of the eNOS and SOD3 being critical in protecting NO from degradation." (PMID 28044093, 2016). "Consistent with this latter report, we found that the plasma level of SOD3 in patients with CAD was not significantly different from that in control subjects, suggesting that SOD3 might do little in the development of atherosclerosis." (PMID 27830142, 2016). "Some reports suggest that SOD3 may play a role in atherosclerosis, but its functional significance is unclear." (PMID 27830142, 2016). "It was concluded that expression of SOD3 in vivo did not directly affect atherosclerosis development." (PMID 28044093, 2016). "Atherosclerosis was not increased in SOD3 knockout mice given an atherogenic diet." (PMID 25855220, 2015).
myocardial infarction (13 papers, 2012 to 2024). Gross necrosis of the myocardium, as a result of interruption of the blood supply to the area, as in coronary thrombosis. "Genetic mutations in SOD3 cause loss of affinity for heparan sulfate and the endothelial cell surface and are associated with polyneuropathy, cardiovascular disease, myocardial infarction, and DM." (PMID 38390944, 2024). "By contrast, a protective T-allele of the rs2284659 variant in the promoter region of the SOD3 gene was negatively associated with the incidence of myocardial infarction and cardiovascular and all-cause mortality in both type 1 and type 2 diabetic patients." (PMID 35277059, 2022). "Targeted adeno-associated viral (AAV) serotype 9 gene transfer of SOD3 via the cardiac troponin T-promoter protected against left ventricular remodeling following myocardial infarction in a murine model." (PMID 34829874, 2021). "We have observed associations of rs2284659 in the promoter of the SOD3 gene with myocardial infarction and with cardiovascular and all-cause mortality in subjects with type 1 or type 2 diabetes." (PMID 25855220, 2015). "In the present study we investigated associations of allelic variation in the SOD3 gene with the risk of myocardial infarction, cardiovascular death and all-cause mortality in two prospective cohorts of type 1 diabetic patients and one prospective cohort of type 2 diabetic patients." (PMID 25855220, 2015). "Alterations in SOD3 activity and its expression have been observed in pathologic processes in various diseases including myocardial infarction, chronic kidney disease, type 2 DM, osteoarthritis, and malignancy." (PMID 35015779, 2022). "A SOD3 R231G variant, which processes less antioxidant ability, was reported to be positively associated with IHD, myocardial infarction, and HF in diabetic subjects." (PMID 35277059, 2022). "The myocardial expressions of SOD3 that remarkably protect against acute myocardial infarction and elevated cardiac SOD3 levels reduce the myocardial infarct size." (PMID 33936387, 2021). "The same group had previously demonstrated that a single direct injection into the left ventricular wall of an AAV serotype 9 gene transfer expressing SOD3 under control of the cardiac troponin T-promoter reduced the size of myocardial infarction in mice." (PMID 34829874, 2021). "The instability of atherosclerotic plaques is related to decreased expressions of SOD3, and the increased cardiac SOD3 levels decrease the myocardial infarct size." (PMID 33936387, 2021). "SOD3 was the most powerful antioxidant enzyme that defended the myocardial infarction by inhibiting reactive oxygen species." (PMID 28044093, 2016). "We investigated association of SOD3 gene variants, plasma concentrations of EC-SOD, AOPP and isoprostane with myocardial infarction and mortality in diabetic patients." (PMID 25855220, 2015). "Further researches may lead to a novel antioxidant agent able either to increase SOD3 levels or to decrease MDA levels for myocardial infarction and chronic heart failure." (PMID 28044093, 2016). "The instability of atherosclerotic plaques is related to decreased expressions of SOD3, and the expressions of SOD3 protect the heart against both myocardial infarction and cardiac remodeling, and the increased cardiac SOD3 levels are shown to decrease the myocardial infarct size." (PMID 33936387, 2021). "Levels of SOD3, NO, eNOS, and MDA in the cardiac tissue were measured in myocardial infarction rats." (PMID 28044093, 2016).
endothelial dysfunction (12 papers, 2014 to 2023). In vascular diseases, endothelial dysfunction is a systemic pathological state of the endothelium (the inner lining of blood vessels) and can be broadly defined as an imbalance between vasodilating and vasoconstricting substances produced by (or acting on) the endothelium. "If an exercise-induced improvement of TAG regulation and endothelial dysfunction was caused by an improvement in oxidative stress, then both PRDX4 and SOD3 would have decreased in the exercise versus control trial for both studies." (PMID 36729923, 2023). "Ang II treatment after renal artery clipping in SOD3 knockout mice developed higher blood pressure and induced endothelial dysfunction, and recombinant SOD3 treatment selectively decreased blood pressure in hypertensive SOD3 knockout mice." (PMID 33477607, 2021). "Furthermore, SOD3 protects against endothelial dysfunction in mice treated with endotoxin." (PMID 26266917, 2014). "In agreement with our finding, it was reported that SOD3 reduces the superoxide level and improves aortic relaxation in response to LPS treatment, but SOD3R213G fails to protect against endothelial dysfunction." (PMID 32004354, 2020). "Meanwhile, in recent similar research work on SOD1 and SOD3 gene transferring indicated that adenoviral-mediated gene transfer of SOD3, but not SOD1, could improve endothelial-dependent relaxation and protect the aorta from xanthine/ xanthine oxidase-mediated endothelial dysfunction." (PMID 30140407, 2018).
pulmonary hypertension (12 papers, 2011 to 2024). Increased pressure within the pulmonary circulation due to lung or heart disorder. "SOD3 is highly expressed in the arterial wall and loss of SOD3 results in alveolar simplification, vascular remodeling, and pulmonary hypertension." (PMID 32854293, 2020). "SOD3 attenuated pulmonary emphysema in an in vivo emphysematic mouse models and SOD3 protected against hypoxia-induced pulmonary hypertension in a mouse model with chronic hypoxia." (PMID 39014439, 2024). "Extracellular superoxide dismutase (ECSOD or SOD3), essential for extracellular ROS homeostasis, has also been closely linked to the development of pulmonary hypertension." (PMID 35204311, 2022). "The lack of experimental evidences supporting the role of ROS in observed exacerbation of pulmonary fibrosis and pulmonary hypertension in Sod3−/− mice is a major limitation of this study." (PMID 30453980, 2018). "Sod3−/− mice showed significantly higher RVSP (33.13 ± 2.17 mmHg) after silica treatment compared to Sod3+/+ mice (p < 0.05) suggesting that SOD3 is protective in the setting of pulmonary hypertension secondary to silicosis." (PMID 30453980, 2018). "SOD3 also appears important for the development of vascular remodeling and pulmonary hypertension in this model." (PMID 30453980, 2018). "In this study, we investigated the protective role of SOD3 in silica-induced lung fibrosis and in pulmonary vascular remodeling and development of pulmonary hypertension." (PMID 30453980, 2018). "For example, SOD1 and SOD3 expression and activity are decreased in chronic hypoxia-induced pulmonary hypertensive mice, rats, calves, and piglets and in a lamb model of persistent pulmonary hypertension of the newborn." (PMID 28666030, 2017). "Moreover, genetic manipulation of SOD3 expression affects the development of pulmonary hypertension in mice exposed to bleomycin or chronic hypoxia." (PMID 30453980, 2018). "Thus, both hemodynamic and morphological features indicate an important role for SOD3 in development of silica-induced pulmonary hypertension." (PMID 30453980, 2018). "Accumulating evidence has suggested that impaired activity of SOD2 and SOD3 contributed to pulmonary hypertension, and the level and activity of SOD1 has not been found significantly changed in human pulmonary hypertension." (PMID 33947399, 2021). "This is important since no previous studies indicated a role for SOD3 in silica-induced pulmonary hypertension." (PMID 30453980, 2018). "The antioxidant enzyme which defends against extracellular O2.−, extracellular superoxide dismutase (EC-SOD or SOD3), is highly expressed in the pulmonary circulation, and its level of expression may modulate the development of pulmonary hypertension." (PMID 22140445, 2011).
chronic obstructive pulmonary disease (10 papers, 2011 to 2025). A chronic and progressive lung disorder characterized by the loss of elasticity of the bronchial tree and the air sacs, destruction of the air sacs wall, thickening of the bronchial wall, and mucous accumulation in the bronchial tree. "Diminished SOD3 activity has been linked to lung diseases such as Acute Respiratory Distress Syndrome (ARDS) or Chronic obstructive pulmonary disease (COPD)." (PMID 35185608, 2022). "Consistent with its important antioxidant function, polymorphisms in SOD3 are associated with reduced lung function and chronic obstructive pulmonary disease (COPD)." (PMID 33014275, 2020). "SOD3 has also been related to inhibition of inflammation, as well as to protection against chronic obstructive pulmonary disease and against renal ischemia/reperfusion injury." (PMID 29707113, 2018).
ischemia (10 papers, 2012 to 2024). A hypoperfusion of the BLOOD through an organ or tissue caused by a PATHOLOGIC CONSTRICTION or obstruction of its BLOOD VESSELS, or an absence of BLOOD CIRCULATION. "Increased EC-SOD levels by adenovirus-mediated transfection of human SOD3 cDNA was associated with protection against myocardial stunning and with decreased reperfusion infarct size in a rabbit model of ischemia/reperfusion injury." (PMID 25855220, 2015). "In addition, it has been shown that SOD3 expression is markedly increased in bone marrow after ischemia and that SOD3 has an essential role in reparative angiogenesis induced by ischemia." (PMID 29707113, 2018). "However, in an experimental model of focal cerebral ischemia, total infarct volume was 81% greater and hemiparesis more severe in SOD3 knockout mice as compared to wild-type animals, while mice overexpressing SOD3 had increased resistance to ischemia." (PMID 25855220, 2015). "Thus, the roles of SOD3 as an antioxidative enzyme in ROS-mediated ischemia and inflammation have been extensively studied." (PMID 24711852, 2014).
lung carcinoma (10 papers, 2017 to 2025). "Superoxide dismutase 3 (SOD3), an antioxidant enzyme, is highly expressed in lung cancer and is associated with worse survival outcomes, suggesting the exploration of the role of SOD3 in chemotherapy resistance." (PMID 40370595, 2025). "In contrast, some studies have reported that high SOD3 expression is associated with a poor survival rate in lung cancer." (PMID 41028519, 2025). "The purpose of this study was to determine the association of SOD3 expression with lung cancer and its potential prognostic relevance by conducting bioinformatics analysis." (PMID 35356201, 2022). "Our paper elaborated and verified the association between SOD3 gene and lung cancer from a fundamental perspective." (PMID 35356201, 2022). "In this experiment and bioinformatic analysis, we determined that the down-regulation of SOD3 was associated with lung cancer growth." (PMID 35356201, 2022). "However, there is the caveat that while SOD3 is generally downregulated in cancers, elevated SOD3 levels have been associated with a poor lung cancer prognosis." (PMID 39480826, 2024). "The SOD3 gene expression in lung cancer cells may be associated with lung cancer patients’ survival rate." (PMID 35356201, 2022). "SOD3 expression was low in lung cancer, and patients with high SOD3 expression had a lower survival rate." (PMID 40867576, 2025). "We also analyzed the difference of SOD3 between the central lung cancer cells and the peripheral lung cancer cells, and divided the cancer cells into four stages for comparison." (PMID 35356201, 2022). "Then in order to investigate the SOD3 presentation in lung cancer cells, we used Western Blot and also applied Flow cytometry to detect the impact of anti-tumor medicine on tumor cell apoptosis." (PMID 35356201, 2022). "We found that the expression level of SOD3 in lung cancer was low (P = 4.218E-29), while the survival of lung cancer patients with high SOD3 expression was shorter (LUSC p =0.00086, LUAD p=0.00038)." (PMID 35356201, 2022). "We analyzed data sets from Gene Expression Comprehensive Database (GEO) and the Cancer Genome Atlas (TCGA), and SOD3 expression was studied in lung cancer." (PMID 35356201, 2022). "The effect of the expression of SOD3 in lung cancer patients survival rate was evaluated by us through multivariate Cox analysis." (PMID 35356201, 2022). "The SOD3 high expression group and the low expression group were compared in lung cancer by GSEA in order to determine the signal pathways activated." (PMID 35356201, 2022). "Through bioinformatics analysis, we found that SOD3 was a possible novel lung cancer gene in this study." (PMID 35356201, 2022). "By comparing the expression of SOD3 in lung cancer, we aim to illustrate the mechanism of SOD3 between normal people and lung cancer patients." (PMID 35356201, 2022). "Through Kaplan-Meier survival analysis, the prognostic value of SOD3 expression was evaluated in lung cancer patients." (PMID 35356201, 2022). "SOD3 gene can be used as a prognostic gene in lung cancer patients, and lung cancer patients with high expression of this gene can reap worse prognostic outcome." (PMID 35356201, 2022). "Despite those limitations, our study is the first study explaining the effect of SOD3 in lung cancer, which will provide theoretical support for future research." (PMID 35356201, 2022). "Therefore, it can be understood that lung cancer cells with low SOD3 expression are more likely to be killed because they cannot break down [O2(-)]." (PMID 35356201, 2022). "This may suggest that the high expression of SOD3 affects the prognosis of patients with lung cancer, making it hard for lung cancer patients to survive longer." (PMID 35356201, 2022). "It showed that cell differentiation was inhibited through downstream expression and regulation of RNA transcription, and the lung cancer occurrence and growth may be improved by SOD3." (PMID 35356201, 2022).